HOXA1 (homeobox A1)
Description:
Sequence-specific transcription factor (By similarity). Regulates multiple developmental processes including brainstem, inner and outer ear, abducens nerve and cardiovascular development and morphogenesis as well as cognition and behavior. Also part of a developmental regulatory system that provides cells with specific positional identities on the anterior-posterior axis. Acts on the anterior body structures. Seems to act in the maintenance and/or generation of hindbrain segments (By similarity). Activates transcription in the presence of PBX1A and PKNOX1 (By similarity).
Synonyms: HOX1F; BSAS; HOX1
Tractability: No criterion of Open Targets' tractability assessment is met for any kind of drug.
Gene: Protein-coding gene on chromosome 7 (27,092,993 to 27,096,000, reverse strand). Ensembl gene ENSG00000105991.
Subcellular location: Nucleus
Pathways (Reactome):
Developmental Biology: Activation of anterior HOX genes in hindbrain development during early embryogenesis
Gene Ontology:
Molecular function: DNA-binding transcription activator activity, RNA polymerase II-specific; identical protein binding; protein binding; sequence-specific DNA binding; sequence-specific double-stranded DNA binding; DNA-binding transcription factor activity, RNA polymerase II-specific; RNA polymerase II cis-regulatory region sequence-specific DNA binding; DNA binding; DNA-binding transcription factor activity
Biological process: abducens nerve formation; anatomical structure morphogenesis; artery development; artery morphogenesis; cochlea development; cochlea morphogenesis; cognition; embryonic neurocranium morphogenesis; inner ear development; neuromuscular process; optokinetic behavior; outer ear morphogenesis; positive regulation of transcription by RNA polymerase II; regulation of behavior; semicircular canal formation; sensory perception of sound; regulation of transcription by RNA polymerase II; regulation of DNA-templated transcription
Cellular component: chromatin; nucleus
Genetic constraint (gnomAD): Loss-of-function variants: 21 observed, 29.89 expected, observed/expected ratio (o/e) 0.7, 90% interval 0.5 to 1.01. The upper end of that interval is the gene's LOEUF score, 1.01, which puts it in group 4 of 6, group 1 being the genes least tolerant of losing a copy. Missense variants: 446 observed, 464.55 expected, observed/expected ratio (o/e) 0.96, 90% interval 0.89 to 1.04. Synonymous variants: 208 observed, 197.09 expected, observed/expected ratio (o/e) 1.06, 90% interval 0.94 to 1.18.
Gene-disease validity (ClinGen):
ClinGen rates the evidence that HOXA1 causes each of these diseases.
syndromic intellectual disability (autosomal recessive): Definitive. A intellectual disability that is part of a larger syndrome.
Homologues: Orthologues: macaque HOXA1 (99% identical), chimpanzee HOXA1 (99% identical), pig HOXA1 (95% identical), rabbit HOXA1 (95% identical), rat Hoxa1 (94% identical), dog HOXA1 (94% identical), mouse Hoxa1 (94% identical), guinea pig HOXA1 (93% identical), tropical clawed frog hoxa1 (70% identical), zebrafish hoxa1a (56% identical). Paralogues in human: HOXB1 (41% identical), HOXD1 (36% identical), HOXB3 (23% identical), HOXD3 (23% identical), HOXD4 (22% identical), HOXA2 (22% identical), HOXA4 (22% identical), HOXA3 (21% identical), HOXB2 (21% identical), HOXC4 (21% identical), HOXB4 (20% identical), HOXD9 (20% identical), and 30 more.
Diseases named in the same sentence as HOXA1 in open-access papers:
HOXA1 is named in the same sentence as 124 diseases in open-access papers, as found by Europe PMC text mining. Sharing a sentence is not in itself a finding about the gene and the disease. The quoted sentences say what the papers report.
breast carcinoma (46 papers, 2009 to 2025). "Most notably, the ER-ACK-KDMA3 signalling nexus significantly upregulates expression of homeobox A1 (HOXA1), a potent oncogene also implicated in breast cancer." (PMID 37194323, 2023). "We previously identified a causal role between HOXA1 expression and NF-κB pathway activation in breast cancer." (PMID 34490074, 2021). "HOXA1 mRNA and protein expression levels were significantly upregulated in breast cancer, and its overexpression was associated with poor prognosis and tumor progression in breast cancer patients." (PMID 32983988, 2020). "On the other hand, Hotairm1 is a long non-coding RNA that has been reported to promote tamoxifen resistance in breast cancer by enhancing HOXA1 upregulation." (PMID 38802425, 2024). "HOXA1 is highly expressed in breast cancer, ovarian cancer, gastric cancer, and various other cancers, which has regulatory roles on cell differentiation, apoptosis, and migration." (PMID 35677036, 2022). "Another study reports that overexpression of circRASSF2 promotes breast cancer progression by modulating miR-1205/homeobox A1 (HOXA1) axis, and its high expression indicates poor prognosis." (PMID 34787066, 2022). "In breast cancer, HOXA1 mediates oncogenic transformation via activation of the p44/42 MAP kinase pathway and is related to endocrine therapy resistance." (PMID 36119466, 2022). "The overexpression of HOXA1 inhibited apoptosis in human mammary carcinoma via activating E‐cadherin signalling pathway cells." (PMID 35411593, 2022). "LncRNA HOTAIR increased resistance to tamoxifen by promoting ER signal transduction; LncRNA HOTAIRM1 promotes breast cancer drug resistance by promoting HOXA1 expression in breast cancer cells." (PMID 35657638, 2022). "Bioinformatic analysis of genome-wide mRNA expression in large public datasets of human breast cancer samples pointed out that HOXA1 mRNA expression is higher in basal-like breast cancer subtype compared to HER2-enriched, luminal A, and luminal B subtypes." (PMID 34490074, 2021). "Second, breast cancer transcriptome analysis highlighted a very strong positive correlation between HOXA1 and NF-κB pathway gene expression." (PMID 34490074, 2021). "For example, HOXA1 gene expression level is reported to enhance proliferation and metastasis in prostate cancer, breast cancer, and gastric cancer and predict poor prognosis in non-small-cell carcinoma." (PMID 33816499, 2021). "HOXA1 mRNA expression showed significant inverse correlation to ER status and PR status of breast cancer samples, in 11 of 12 datasets." (PMID 34490074, 2021). "To further explore an oncogenic role for HOXA1 in breast cancer, we examined HOXA1 mRNA expression in public genome-wide mRNA expression datasets of human breast cancer samples." (PMID 34490074, 2021). "For instance, HOXA1 mRNA and protein expression is upregulated in breast cancer, and forced expression of HOXA1 in human breast cancer cells resulted in increased cell proliferation and doxorubicin resistance." (PMID 32296636, 2020). "Collectively, our study demonstrates that SNHG1 promotes breast cancer cell proliferation and metastasis by acting as a sponge of miR-193a-5p to activate HOXA1 expression." (PMID 32497022, 2020). "HOXA1 played a role of an oncogene in breast carcinoma, lung carcinoma, oral squamous cell carcinoma, hepatocellular carcinoma, melanoma, gastric cancer, leukemia and retinoblastoma (RB)." (PMID 33763449, 2020). "The expression level of HOXA1 in subtypes of breast cancers are related to the disordered epigenetic activity, in which the methylation frequency of Luminal B is the highest (< 0.001)." (PMID 33763449, 2020). "Our study focused on the mechanism by which HOTAIRM1 regulates HOXA1 in tamoxifen-resistant breast cancer cells." (PMID 32284737, 2020).
breast carcinoma (continued). "In breast cancer, HOXA1 has been identified as a breast epithelial oncogene whose forced expression is sufficient to induce the transformation of immortalized human mammalian epithelial cells into aggressive cancer cells." (PMID 33763449, 2020). "Here, we show that SNHG1 is an oncogenic lncRNA that interacts with miR-193a-5p to reduce its repression of the HOXA1 gene and thus accelerate breast cancer development." (PMID 32497022, 2020). "At present, HOXA1 small interfering RNA (siRNA) nanoparticles have achieved initial success in mouse models of breast cancer and are effective (75%) to reduce the incidence of tumors." (PMID 33763449, 2020). "E-cadherin activated Rac signaling pathway through the transcription target of HOXA1, which can promote breast cancer cell survival by upregulating cyclinD1, c-Myc, and BCL-2." (PMID 33763449, 2020). "Together, these data suggest that SNHG1 acts as a sponge to inhibit miR-193a-5p and thus activates HOXA1 expression in breast cancer cells." (PMID 32497022, 2020). "In breast cancer, HOXA1 transforms immortalized human breast epithelial cells stimulated by p44/42 MAPK pathway, signal transducer and activator of transcription 3 (STAT3) and STAT5B into an invasive malignant phenotype." (PMID 33763449, 2020). "In previous reports, the abnormal expression of HOXA1 is related to the prognosis of breast cancer, lung cancer, liver cancer, prostate cancer, oral cancer, gastric cancer and melanoma." (PMID 33763449, 2020). "Conversely, HOTAIRM1 promotes breast cancer, lung cancer, and pancreatic ductal adenocarcinoma by directly regulating HOXA1 expression." (PMID 31477638, 2019). "The expression of HOXA1 was significantly increased in regulatory therapy but was significantly downregulated in MCF-7 breast cancer cells treated with ACK1 inhibitor AIM-100 and dasatinib." (PMID 31772931, 2019). "The newly identified miR-99a/HOXA1 axis provides novel insight into the pathogenesis of breast cancer, and represents a potential therapeutic target for the treatment of breast cancer." (PMID 26417931, 2015). "Using three miRNA target prediction algorithms (TargetScan, PicTar and miRanda), we provided the first demonstration that HOXA1 mRNA is a direct functional target of miR-99a in breast cancer." (PMID 26417931, 2015). "Here, we demonstrate for the first time that HOXA1 was frequently up-regulated in breast cancer tissues." (PMID 26417931, 2015). "HOXA1-stimulated oncogenicity is mediated by selective upregulation of components of the p44/42 MAP kinase pathway in human mammary carcinoma cells." (PMID 26080812, 2015). "HOXA1 mRNA levels were significantly higher in breast cancer tissues than in adjacent normal tissues (P = 0.0351)." (PMID 26417931, 2015). "The HOXA1 is an ER-regulated gene and the HOXA1 locus is believed to be involved in promoting growth of tamoxifen resistant breast cancer cells." (PMID 26473850, 2015). "Taken together, these findings indicated that HOXA1 mRNA is a direct, down-stream target of miR-99a in breast cancer cells." (PMID 26417931, 2015). "Conversely, overexpression of HOXA1, which is a direct functional target of miR-99a, promoted breast cancer cell growth and metastasis." (PMID 26417931, 2015). "Knockdown of HOXA1 significantly inhibited breast cancer cell proliferation, migration and invasion, and restoration of HOXA1 partially rescued the inhibitory effect of miR-99a in breast cancer cells." (PMID 26417931, 2015). "In a recent article, Brock and colleagues reported that overexpressed HOXA1 is a critical event in tumor progression in a mouse mammary tumor model." (PMID 25927933, 2014). "Hoxa1 activation is required for E-cadherin-dependent anchorage-independent proliferation and decreases apoptotic cell death of human mammary carcinoma cells." (PMID 21957483, 2011). "Hoxa1 has been reported to be abnormally expressed in breast carcinomas and to act as a mammary oncogene." (PMID 21957483, 2011).
breast carcinoma (continued). "Hoxa1 has previously been shown to affect the phenotype of the epithelioid mammary tumor cell line MCF7 in a way that is indicative of its pro-oncogenic activity, as its forced expression enhanced cell proliferation and anchorage-independent growth." (PMID 21957483, 2011). "HOXA1 is known to be an oncogene in breast cancer, glioma, and gastric cancer." (PMID 37834206, 2023). "In human mammary carcinoma, HOXA1 could enhance the expression and phosphorylation of STAT3 and STAT5B to promote cell survival and proliferation." (PMID 34617205, 2022). "HOXA1 was found to upregulate the expression of BCL2 in breast cancer, which could also enhance cell proliferation and promote malignant transformation of cancer cells by activating STAT5a/b and MAPK signaling pathways." (PMID 35677036, 2022). "HOXA1 was notably found to be involved in different types of cancer, including liver, stomach, lung, prostate, endometrium, and breast cancers." (PMID 34490074, 2021). "We analyzed whether HOXA1 expression levels were correlated to the three main breast cancer molecular markers: ER, PR, and HER2." (PMID 34490074, 2021). "We have earlier uncovered the ability of HOXA1 to activate the NF-κB pathway after finding strong correlations between the mRNA expression of HOXA1 and players of the NF-κB signaling network in public datasets of human breast cancer samples." (PMID 34490074, 2021). "We recently addressed the molecular mechanisms of HOXA1 action in breast cancer." (PMID 34490074, 2021). "Interestingly, HOXA1 expression was significantly correlated to breast cancer molecular subtypes as well." (PMID 34490074, 2021). "For example, what needs to be determined is to what extent genes with mRNA expression that is oppositely correlated to HOXA1 and ERα in breast cancer correspond to shared direct target genes, on which the HOXA1-ERα molecular interaction will be translated into a functional transcription output." (PMID 34490074, 2021). "HOXA1 expression has been shown to be strongly correlated to poor prognosis in breast cancer." (PMID 34490074, 2021). "To examine whether HOTAIRM1 functions as a regulator of the adjacent HOXA1 gene transcription in tamoxifen-resistant breast cancer cells, we treated TAMR cells with siHOTAIRM1 and examined the expression of anterior HOXA genes." (PMID 32284737, 2020). "Our results revealed a novel mechanism which demonstrates that HOTAIRM1 and HOXA1 could be promising therapeutic targets for patients with ER+ breast cancer who have acquired tamoxifen resistance." (PMID 32284737, 2020). "Furthermore, HOXA1 overexpression can eliminate the effect of SNHG1 silencing in breast cancer cells." (PMID 32497022, 2020). "Further exploration of the molecular mechanisms of the HOTAIRM1/HOXA1 axis may provide more insight in the pathogenesis of breast cancer." (PMID 32284737, 2020). "To further validate the clinical relevance of HOTAIRM1 and HOXA1, we analyzed a publicly available clinical in silico dataset comparing 60 paired primary ER+ breast cancer patients to recurred cancer patients following tamoxifen mono-therapy for 5 years (GSE1379)." (PMID 32284737, 2020). "HOXB13, HOXA10 and HOXA1 genes are hyper-methylated in breast cancer patients." (PMID 33225883, 2020). "To confirm that HOXA1 is involved in the SNHG1 pathway in breast cancer progression, we tested whether enforced HOXA1 expression would eliminate the effect of SNHG1 silencing in MDA-MB-231 cells." (PMID 32497022, 2020). "Also, activity of histone demethylase KDM3A has been found to play an important part in the mediation of oncogene HOXA1 expression in breast cancer." (PMID 33520978, 2020). "We focused on the HOXA1 gene in this study as is a potential oncogene in breast cancer." (PMID 32497022, 2020). "Besides, forced expression of HOXA1 in human mammary carcinoma cells resulted in increased proliferation and decreased apoptotic cell death in a Bcl-2-dependent manner." (PMID 31507632, 2019).
breast carcinoma (continued). "For example, miR-18a downregulates PTEN and HOXA1 to promote breast cancer progression." (PMID 29258605, 2017). "Therefore, we first tested the HOXA1 mRNA levels in 31 breast cancer patient samples and their corresponding normal breast tissues." (PMID 26417931, 2015). "Furthermore, we identified HOXA1, a putative oncogene in breast cancer, as a direct and functional target of miR-99a." (PMID 26417931, 2015). "Restoration of HOXA1 expression rescued the inhibitory effect of miR-99a in breast cancer." (PMID 26417931, 2015). "Furthermore, we showed for the first time that HOXA1 expression is elevated in breast cancer tissues." (PMID 26417931, 2015). "Therefore, our study demonstrated that miR-99a suppresses the progression of breast cancer by inhibiting HOXA1 function." (PMID 26417931, 2015). "A previous study found that substitution of the tryptophan and the fifth residue of HOXA1 suppressed its oncogenic activity in breast cancer, indicating that the Hox-Pbx interaction was mediated by the hexapeptide motif of Hox and is essential to perform its oncogenic role." (PMID 26536658, 2015). "In addition, among all predicted targets of miR-100, HOXA1 is a mammary oncogene and is upregulated in human breast cancer; overexpression of HOXA1 in immortalized human mammary epithelial cells was sufficient to induce aggressive tumor formation in vivo." (PMID 24586203, 2014). "Oncomine database analysis strengthened their hypothesis since HOXA1 was found to be overexpressed in human breast cancers." (PMID 25927933, 2014). "Furthermore, HOXA1 is a downstream effector of E-cadherin-directed signaling required for anchorage-independent proliferation of mammary carcinoma cells." (PMID 22498108, 2012). "In breast cancer, HOXA1 was identified as a frequently methylated, and in an analysis similar to ours, was found to be significantly hypermethylated in atypical ductal hyperplasia (ADH) relative to normal breast, and ductal carcinoma in situ (DCIS) relative to ADH." (PMID 21731750, 2011). "Furthermore, Hoxa1 promotes the activation of Cyclin-D1 required for the autocrine hGH-mediated cell cycling stimulation in mammary carcinoma." (PMID 21957483, 2011). "Therefore, early de novo HOXA1 expression in the mammary gland might lead to the development of aggressive subtypes of breast cancer, and late HOXA1 expression in an ER+ tumor environment might lead to endocrine therapy resistance." (PMID 34490074, 2021). "However, the regulatory role of HOTAIRM1 on HOXA1 transcription in breast cancer, more specifically tamoxifen-resistant breast cancer, remains unknown." (PMID 32284737, 2020). "Furthermore, reduced expression of HOXA1 could inhibit breast cancer cell proliferation, migration and invasion." (PMID 26417931, 2015). "However, the biopathological significance of HOXA1 in human cancer, especially breast cancer, is still largely unknown." (PMID 26417931, 2015). "However, the biological function of HOXA1 in breast cancer remains poorly understood." (PMID 26417931, 2015). "In addition, ectopic expression of HOXA1 in MCF7 breast cancer cells upregulated cyclin D1, a cyclin that is required for steroid-induced proliferation of mammary epithelium during pregnancy and promotes the development of mammary adenocarcinomas when overexpressed." (PMID 24586203, 2014). "These interactions reveal the complex mechanisms of miR-193a-5p in cancer development.miR-193a-5p inhibits breast cancer progression by targeting SNHG1 and inactivating the oncogene HOXA1." (PMID 40161373, 2025). "The expression levels of LincRNA H19, miR-675, MRP3, HOXA1, and MMP16 in breast cancer tissues also suggest a strong link with the early onset and types of breast cancer, with MRP3 showing high prognostic value." (PMID 39267845, 2024). "Correlations of LincRNA H19, miR-675, MRP3, HOXA1, and MMP16 with clinicopathological parameters in patients with breast cancer." (PMID 39267845, 2024).